IL6 (interleukin 6)
Diseases named in the same sentence as IL6 in open-access papers (continued):
Sharing a sentence is not in itself a finding about the gene and the disease.
endothelial dysfunction (continued). "IL-6 triggers proinflammatory signaling through soluble IL-6 receptor binding and subsequent JAK/MAPK and NF-κB pathway activation, resulting in oxidative stress, endothelial dysfunction, and retinal inflammation." (PMID 40880763, 2025). "Also, reductions in the C-reactive protein (CRP), TNF-α, and IL-6 further illustrate the anti-inflammatory properties of GLP-1RAs, which play a crucial role in mitigating ischemia–reperfusion injury and endothelial dysfunction." (PMID 38675485, 2024). "In the pediatric population, increased waist-to-hip ratio has been associated with elevated markers of inflammation, including CRP, IL-6, and MCP-1, as well as with markers of endothelial dysfunction, such as soluble intracellular cell adhesion molecule-1 (sICAM)." (PMID 38396489, 2024). "These processes lead to endothelial dysfunction and a pro-inflammatory state, characterized by increased circulating levels of inflammatory cytokines such as tumor necrosis factor-alpha (TNF-α) and interleukin-6 (IL-6)." (PMID 39596237, 2024). "In our study, the result of correlation coefficient of inflammatory markers (IL-6, IL-8) and endothelial dysfunction marker (ICAM, VCAM) with biochemical marker urea and creatinine of overall (IL-6, IL-8, ICAM, VCAM × urea, creatinine) had a statistical significantly positive correlation." (PMID 38961103, 2024). "This indicates that IL-6 may contribute to the pathogenesis of CSX by promoting inflammation and initiating endothelial dysfunction, which leads to reduced vascular reactivity, specifically microvascular vasoconstriction." (PMID 38807048, 2024). "These pathways stimulate the release of proinflammatory cytokines and chemokines, such as interleukin-6 (IL-6) and tumor necrosis factor-alpha (TNF-α), which promote inflammation and endothelial dysfunction, recruit immune cells to the site of injury and exacerbate the inflammatory response." (PMID 39539435, 2024). "IL-6 plays a central role in the inflammatory cascade and may contribute to the pathogenesis of ARDS by promoting endothelial dysfunction, alveolar epithelial injury, and the recruitment of inflammatory cells." (PMID 39416868, 2024). "In our study, the result of correlation coefficient of inflammatory markers (IL-6, IL-8) and endothelial dysfunction marker (ICAM, VCAM) with biochemical marker glycolytic hemoglobin (HbA1c) of overall (IL-6, IL-8, ICAM, VCAM × HbA1c) had a statistical significantly positive correlation." (PMID 38961103, 2024). "Proinflammatory cytokines such as IFN-gamma, IL-6, IL-10, and TGF-beta, which are increased due to ischemic stroke, might link the brain ischemia to endothelial dysfunction." (PMID 39311310, 2024). "In addition, IL-6 activates chronic inflammation through the JAK/STAT pathway and increases the expression of adhesion molecules in the vasculature, leading to endothelial dysfunction, monocyte/macrophage recruitment and smooth muscle cell migration." (PMID 39717442, 2024). "Inflammatory cytokines, such as IL-6 and TNF-α, are upregulated in H. pylori infections, leading to endothelial dysfunction, and studies found that these cytokines contribute to oxidative stress and reduce NO availability, critical factors in endothelial impairment." (PMID 39202269, 2024). "In our study, the result of correlation coefficient of inflammatory markers (IL-6, IL-8) and endothelial dysfunction marker (ICAM, VCAM) with biochemical marker AST, CKMB and CRP of overall (IL-6, IL-8, ICAM, VCAM × AST, CKMB and CRP) had a statistical significantly positive correlation." (PMID 38961103, 2024). "IL-6 stimulates CRP production, promotes endothelial dysfunction, and leads to plaque instability." (PMID 39057626, 2024). "Endothelial dysfunction was observed in PA-treated HAECs, including impaired total antioxidant capacity, cell viability, NO levels, and eNOS, MFN2 and UQCRC1 protein levels, as well as significant up-regulation of IL6, MMP1, and CHOP mRNA levels." (PMID 37237885, 2023).
endothelial dysfunction (continued). "In contrast to sC3M, uC3M was only correlated with IL-6 in adjusted analyses, and not correlated with any of the other markers of inflammation and was positively correlated with only one of the markers of endothelial dysfunction." (PMID 36930632, 2023). "We determined associations between components of the classical (PRA-S, Ang I, Ang II) and alternative RAS (Ang 1–7) and parameters of liver disease severity (i.e. MELD), LSM, portal hypertension (i.e. HVPG), endothelial dysfunction (i.e. VWF antigen) and inflammation (i.e. IL-6)." (PMID 36653504, 2023). "There is evidence that chemerin may enhance the expression of various inflammatory factors, such as IL-6, TNFα, and CRP, resulting in blood vessel wall inflammation, increased monocyte attachment to endothelial cells, and endothelial dysfunction." (PMID 37107205, 2023). "Furthermore, a study on microcirculatory endothelial cells (HMEC-1) was performed to evaluate the potential reduction of some markers of endothelial dysfunction (LOX-1 and IL-6), which are increased in a condition of oxidative stress and inflammation." (PMID 37372038, 2023). "In fact, LPS induce endothelial dysfunction, increase oxidative stress through production of reactive oxygen species (ROS), and produce several pro-inflammatory cytokines, such as TNF-α, interleukin-1 (IL-1), interleukin-6 (IL-6), and interleukin-8 (IL-8)." (PMID 36982492, 2023). "Indeed, the role of TMAO in the modulation of factors strictly related to the development of endothelial dysfunction, such as nitric oxide, adhesion molecules (ICAM-1, VCAM-1, and selectins), and IL-6, has been widely accepted." (PMID 36982880, 2023). "Other factors circulating in the maternal blood during PE including pro-inflammatory cytokines (IL-6), AT1-AA, and free fetal hemoglobin (HbF) may also intensify oxidative stress and endothelial dysfunction." (PMID 37107205, 2023). "Given the prominent role of IL-6 in endothelial cell dysfunction and the specific upregulation of IL-6 by CAEC in response to IL-32 we aimed to determine the impact of the IL-32 isoforms on the typical endothelial dysfunction markers ICAM-I and VCAM-I." (PMID 36992409, 2023). "In addition, it alleviated endothelial dysfunction, led to a decrease in serum E-selectin and ICAM-1, and decreased the level of pro-inflammatory cytokines IL-6 and TNF-α in the serum and MPO, as well as the MDA of the oxidative stress marker." (PMID 37371797, 2023). "Upon endothelial damage, there is an increase in proinflammatory molecules such as interleukin-1 (IL-1), interleukin-6 (IL-6), tumor necrosis factor alpha (TNF-α) and C-reactive protein (CRP) leading to a proinflammatory endothelium and endothelial dysfunction." (PMID 35455027, 2022). "Further, silibinin may reduce pro-inflammatory effects and endothelial dysfunction by regulating expression patterns of TNF-α, IL-6 and ET-1 in blood plasma." (PMID 35821883, 2022). "Studies have shown that the ACE2-Ang II axis can induce the infiltration of macrophages and secretion of certain cytokines, including IL-6, CCL2, vascular cell adhesion molecule 1 (VCAM-1), and E-selectin, to induce endothelial dysfunction, thrombin formation, and impaired fibrinolysis." (PMID 35464491, 2022). "In OSA patients, repeated oxygen desaturations and subsequent endothelial dysfunction induce the release of strong proinflammatory biomarkers, particularly tumor necrosis factor alpha (TNF-α), interleukin-6 (IL-6), C-reactive protein (CRP), leptin, and reactive oxygen species (ROS)." (PMID 34349888, 2021). "In our study, markers of endothelial dysfunctions (IL6, sgp130, sVCAM1, sICAM1) were not significant after multivariate adjustment." (PMID 33868296, 2021).
endothelial dysfunction (continued). "There are several possible pathways that are thought to be involved in the formation and progression of AS by IL-6: 1) IL-6 induces CRP production in the liver to stimulate leukocyte recruitment and promote inflammatory responses in endothelial cells, leading to endothelial dysfunction." (PMID 34504432, 2021). "Patients with IBD have an increased production of reactive oxygen species (ROS), increased expression of inflammatory cytokines (TNF-⍺ and IL-6) and antibodies that lead to vascular smooth muscle cell proliferation (VSMC), endothelial dysfunction, and the development of CVD." (PMID 34682835, 2021). "Taken together, the increased levels of IL-1α, IL-6, and TNF-α in MSK1/2 KO mice could explain the observed endothelial-dysfunction in this study, although the mechanisms of diminished NO bioavailability may be multi-modal and requires further scrutiny." (PMID 34445361, 2021). "An inflammatory environment together with an enlarged amount of the proinflammatory cytokine immunoglobulin 6 (IL-6) is connected with increased AT1R expression on endothelial cells and may stimulate endothelial dysfunction." (PMID 33499235, 2021). "The pro-inflammatory cytokine storm, with elevated levels of interleukin-6 (IL-6), IL-2 receptor, and tumor necrosis factor (TNF)-α, could also participate in endothelial dysfunction and leukocyte recruitment in the microvasculature." (PMID 32903391, 2020). "Other authors have shown attenuating in vitro effects of urolithin A on endothelial dysfunctions induced by oxidized LDL through the beneficial modulation of TNF-α, IL-6, endothelin 1, PPAR-γ, ICAM-1 (intercellular adhesion molecule 1), and MCP-1 (monocyte chemotactic protein 1) expression." (PMID 33322602, 2020). "Proinflammatory cytokines such as tumor necrosis factor-α (TNF-α) and interleukin-6 (IL-6) and hypoxia-inducible factor (HIF), reactive oxygen species and angiotensin II type 1 receptor, all are involved in the development of the endothelial dysfunction and preeclampsia." (PMID 31737362, 2019). "In our data, the expression of IL-6, IL-1β, and MMP-9 increased in the intestinal tissues of the irradiated group and the result suggested that intestinal inflammation is accompanied by endothelial dysfunction in radiation-induced intestinal injury." (PMID 31474856, 2019). "Inflammatory markers (TNF-α, IL-6, hsCRP) and endothelial dysfunction markers (E-selectin, ICAM-1, VCAM-1) between MetS and non-MetS patients by gender." (PMID 31550292, 2019). "IL-6 may be involved in the pathogenesis of HTN through its effects on vascular inflammation and stiffness and endothelial dysfunction." (PMID 31186952, 2019). "Based on the current findings, IL-1RA, IL-2, IL-4, IL-6, GM-CSF and IFN-γ were elevated to remarkably high levels in DM-SFTS patients, likely contributing to the fatal outcome, together with the development of depressed immunity and endothelial dysfunction." (PMID 31136581, 2019). "Among the markers of inflammation and endothelial dysfunction in patients with and without MetS, males with MetS had significantly higher levels of IL-6 and hsCRP than the non-MetS group, and also had higher E-selectin levels but without significance." (PMID 31550292, 2019). "Moreover, interesting correlations were observed between IL-6 and the early markers of acute kidney injury (KIM-1 and L-FABP) as well as the markers of endothelial dysfunction (Ang-2 and sFlt-1)." (PMID 29925813, 2018). "Its correlation with serum levels of biological markers that could participate in endothelial dysfunction pathways such as NO3−/NO2− ratio, NO2−, citrulline, TNFα, IL-1, IL-6, IL-10, IL-8, osteopontin, ICAM, VCAM, and NO3−/NO2− was determined." (PMID 30246778, 2018). "During RA, the increased expression of TNF-α, IL-1β, IL-6, adhesion molecules, angiotensin II type 1 receptor, and endothelin, together with a lower expression of NO, might contribute to SAH via endothelial dysfunction." (PMID 28103312, 2017).
endothelial dysfunction (continued). "In adiposity, excess secretion of various pro-inflammatory cytokines, chemokines, and proteases, such as TNF-α, IL-6, MCP-1, leptin, and PAI-1, by infiltrating macrophages and T cells around the adipose tissue, leads to endothelial dysfunction, oxidative stress, and inflammation activation." (PMID 28182687, 2017). "Escin significantly ameliorated endothelial dysfunction (increased serum E-selectin and ICAM-1 and lung Wet/Dry ratio, decreased serum NO), and oxidative and inflammatory responses (increased serum MDA, MPO, IL-6 and TNF-α) (P < 0.05 or P < 0.01)." (PMID 28112272, 2017). "In our study, NPY, CA, AngII, ET-1, CRP, IL-6, and TNF-α increased while MT decreased after SD, which is characteristic of the beginning of myocardial injury due to hormone disorders, inflammation, and endothelial dysfunction." (PMID 28479928, 2017). "Based on our novel findings of the possible interactive influence between TNF-α and IL-6, we believe that an anti-inflammatory strategy blocking IL-6 and/or TNF-α may effectively prevent T2D-mediated endothelial dysfunction in coronary microcirculation." (PMID 29095915, 2017). "With regard to future directions, it would be of interest to support our findings with measuring markers of endothelial dysfunction, such as adhesion molecules (i.e., intracellular adhesion molecule 1, ICAM-1), cytokines (interleukin 6, IL-6), matrix metalloproteinases." (PMID 28918499, 2017). "IL‐6 also produced marked increases in both basal‐ and NADPH‐stimulated superoxide levels in aorta from eNOS+/− mice, providing a mechanistic link between plasma IL‐6 levels and the endothelial dysfunction observed in eNOS+/− mice fed a HFD." (PMID 26660551, 2015). "Significant disease associations have been shown between vascular function, high sensitive-CRP (hs-CRP), and interleukin-6 (IL-6) in RA and SLE patients, suggesting a link between systemic cytokine overexpression and endothelial dysfunction, an early event in the development of CVD." (PMID 25648164, 2015). "The exact mechanism responsible for the onset of endothelial dysfunction in ABIN1[D485N] mice requires further investigation; however, this may be mediated by IL-6." (PMID 25648164, 2015). "In addition, vascular inflammation plays a critical role in endothelial dysfunction which can be induced by the production of pro-inflammatory cytokines such as tumor necrosis factor-alpha (TNF-α) and interleukin-6 (IL-6)." (PMID 24223557, 2013). "A subset of the COVID patient cohort was tested for pro-inflammatory biomarkers: IL-32 displayed an inverse correlation with patients' neutrophil-to-lymphocyte ratio (NLR) (estimate -0.23 ± 0.81; p=0.005) and not with IL-6 and biomarkers of endothelial dysfunction (n=42, p=NS)." (PMID 41727490, 2026). "Preclinical studies have shown that metformin regulates endotoxemia-induced endothelial dysfunction and inflammation through the AMPK/KLF2 axis, restoring KLF2 levels reduced by LPS and TNF-α stimulation, and inhibiting VCAM1 expression while reducing inflammatory factors like TNF-α and IL-6." (PMID 41373858, 2025). "The study aimed to demonstrate the presence of endothelial dysfunction in patients with moderate COVID-19 infection using flow-mediated dilatation (FMD) of the brachial artery and to evaluate its correlation with key inflammatory markers (erythrocyte sedimentation rate—ESR, fibrinogen, NLR, IL-6)." (PMID 40143236, 2025). "In addition, IL‐6 increases smooth muscle cell proliferation and migration, activation of macrophage‐monocytes, intima cell migration and LDL oxidation in coronary arteries, which lead to endothelial dysfunction." (PMID 39264256, 2024). "Periodontal disease can lead to elevated levels of inflammatory markers such as C-reactive protein (CRP), interleukin-6 (IL-6), and tumor necrosis factor-alpha (TNF-α), which may contribute to endothelial dysfunction and impaired placental blood flow, thereby increasing the risk of pre-eclampsia." (PMID 39401230, 2024).
endothelial dysfunction (continued). "In this regard, it has been shown that endothelial dysfunction, a major feature of CVD, can also be induced by chronic periodontal infection, due to a systemic pro-inflammatory condition, as suggested by increased plasma levels of acute phase proteins, IL-6 and fibrinogen." (PMID 37374981, 2023). "Furthermore, IFN- γ, TNFα, and IL-6 have been shown to induce hypoxia which promotes endothelial dysfunction; however, the mechanisms are not fully established." (PMID 37937252, 2023). "Additionally, an AngII-dependent increase in serum IL-6 concentration is also shown to induce downstream activation of STAT3 pathways and inhibit eNOS expression, leading to a decrease in NO and the promotion of endothelial dysfunction." (PMID 37238657, 2023). "While we observed no direct cell effect of Empa or Dapa on LPS-induced IL-6 release, attenuated markers of endothelial dysfunction, i.e., ROS and nitric oxide, have been reported in activated endothelial cells exposed to Empa or Dapa, but without change in the expression of adhesion molecules." (PMID 33048256, 2021). "Many cytokines such as TNF-alpha, IL-1, IL-2, IL-4, IL-6, IL-18, monocyte chemoattractant protein-1 (MCP-1), vimentin, and platelet-derived growth factor (PDGF) are produced by macrophages and T lymphocytes activated due to endothelial dysfunction and oxidative stress." (PMID 34349888, 2021). "Patients with MetS may also exhibit micro-albuminuria, endothelial dysfunction and a pro-inflammatory and pro-thrombotic state, with increased circulating C-reactive protein (CRP), tumor necrosis factor-α (TNF-α) and interleukin-6 (IL-6)." (PMID 33777773, 2021). "If SAA-stimulation leads to production of IL-6 by a dysfunctional endothelium, then this interleukin may induce the production of additional SAA, thereby establishing an autocrine loop and effectively exacerbating endothelial dysfunction." (PMID 30597899, 2018). "Therefore, we hypothesized that IL-6 is a critical contributor to coronary endothelial dysfunction in T2D and that the interaction between IL-6 and TNF-α exacerbates endothelial dysfunction." (PMID 29095915, 2017). "In conclusion, impaired endurance running capacity in IL-6−/− mice could not be explained by reduced V′O2max, endothelial dysfunction or impaired muscle oxidative capacity." (PMID 24533077, 2014). "Because IL-6 upregulates AT1R gene expression, it may lead to increased Ang II-mediated vasoconstriction and ROS production, and thereby play an important role in mediating endothelial dysfunction." (PMID 19936194, 2008). "It is therefore not surprising that ADMA has been associated with endothelial dysfunction among multiple organ systems, cardiovascular and noncardiovascular, as its presence is associated with increased levels of inflammatory cytokines, including IL-1β, TNF-α, IL-6, IL-10, IL-4, IL-2, and more." (PMID 39941130, 2025). "In addition, co-treatment with PA and NAC reduced endothelial dysfunction, including restoration of total antioxidant capacity, cell viability, NO levels, and eNOS, DRP1, MFN2, NDUFS3, and UQCRC1 protein levels, as well as inhibition of IL6 and CHOP mRNA levels." (PMID 37237885, 2023). "Likewise, our data showing that plasma IL-6 levels did not correlate with endothelial dysfunction strongly suggest that the benefits provided by nor-NOHA are related to the direct modulation of endothelium-derived vasorelaxant pathways rather than an anti-inflammatory effect." (PMID 22647483, 2012). "Our patients also had higher hs-CRP and IL-1, IL-6 and TNF-α concentrations than did control individuals, but these nontraditional cardiovascular risk factors did not fully account for the differences in biomarkers of endothelial dysfunction between patients and control individuals." (PMID 15899050, 2005).